CCL4 (C-C motif chemokine ligand 4)
Diseases named in the same sentence as CCL4 in open-access papers (continued):
Sharing a sentence is not in itself a finding about the gene and the disease.
cardiovascular diseases (9 papers, 2009 to 2025). "In this part, we focus on the background of CCR5 and its interactions with CCL4 in DM and cardiovascular diseases." (PMID 27553774, 2016). "It seems that the modulation of CCL4 in some clinical cardiovascular diseases, such as hypertension, is mainly related to the presence of type 2 DM." (PMID 27553774, 2016). "Recent findings demonstrated that both CCL4 and its receptor CCR5 play diverse roles in the inflammatory events underlying DM and cardiovascular diseases." (PMID 27553774, 2016). "Given the potential impacts of CCL4 upon various cardiovascular diseases, we hypothesized that CCL4 might play a mechanistic role in aging-related vascular dysfunction." (PMID 38739303, 2024). "In this review, we provide an overview of the role and potential mechanisms of CCL4 and one of its major receptors, fifth CC chemokine receptor (CCR5), in DM and cardiovascular diseases." (PMID 27553774, 2016). "Previous studies have reported a reduction of plasma chemokines (i.e CCL2, CCL4, CXCL8) in patients with cardiovascular disease treated with statins." (PMID 19421322, 2009).
inflammation (9 papers, 2017 to 2024). Aberrant reaction of the microcirculation characterized by movement of fluid and leukocytes from the blood into extravascular tissues. "Although CCL4 was mainly associated with mononuclear cells and released from them, activated eosinophils are also sources, especially in airway inflammation." (PMID 35892679, 2022). "Collectively, while CCL4 increased with aging and could induce endothelial inflammation, either intrinsic deficiency or external blockage of CCL4 may significantly attenuate aging related vascular impairment both in vitro and in vivo." (PMID 38739303, 2024). "Thus, CD69 was positively correlated to CCL4, indicating that CCL4-mediated eosinophil activation is associated with eosinophilic airway inflammation." (PMID 36555793, 2022). "This is illustrated by their strong expression of pro-inflammatory mediators including chemokines (e.g. Ccl3, Ccl4) and members of the IL-1 family, such as Il1f9 (encoding for IL-36γ) that was specifically expressed by neutrophils and recently identified as an amplifier of pulmonary inflammation." (PMID 38348034, 2024). "CCL4 is a key cytokine released from eosinophils and epithelial cells in eosinophilic airway inflammation, and its level is high in mucin obtained from patients with ECRS." (PMID 39791734, 2024). "Furthermore, we identified a positive correlation between serum CCL4 and CCL17 levels, suggesting that serum CCL4 could be a relatively specific marker for type 2 airway inflammation." (PMID 35892679, 2022). "Moreover, the presence of ILC-like cells expressing CCL4 and CXCL8 may contribute to the effects of the cNK cells in the perpetuation of liver inflammation since these chemokines are chemoattractants for neutrophils and immature dendritic cells." (PMID 37063898, 2023).
neurodegenerative disease (6 papers, 2021 to 2025). A disorder of the central nervous system characterized by gradual and progressive loss of neural tissue and neurologic function. "Ccl4 and Ccl5 are mainly involved in the infiltration and activation of immune cells, including microglia, and have been implicated in the progression of several neurodegenerative diseases." (PMID 36551859, 2022). "The data presented in this paper supports a role of CCL4 in the pathogenesis of neuroinflammatory and neurodegenerative diseases." (PMID 34755124, 2021).
adenocarcinoma (4 papers, 2020 to 2024). A common cancer characterized by the presence of malignant glandular cells. "CCL2 and CCL4 overexpression was associated with beneficial OS and PFS in squamous NSCLC, but unfavorable OS and PFS in adenocarcinoma NSCLC." (PMID 33230935, 2021). "In adenocarcinomas, the expression ratios (normal-to-pathological) of ACKR2 were positively correlated with all those chemokines while in polyps, with CCL3 and less markedly with CCL4 and CCL7." (PMID 33374792, 2020).
immune dysfunction (3 papers, 2022 to 2024). "MIP-1b, also known as chemokine (CC motif) ligand 4 (CCL4), is a powerful chemokine and can enhance immune system disorders by recruiting regulatory T cells and macrophages, which eventually results in organ lesions." (PMID 35966818, 2022).
infectious disease (3 papers, 2020 to 2022). A disorder directly resulting from the presence and activity of a microbial, viral, or parasitic agent in humans. "DNA vaccine (CyHV-2 ORF25) conjugated with molecular adjuvant CCL35.2 (mammalian CCL4 analogue) remarkably improved the survival rate of gibel carp against CyHV-2 infection (a fulminating infectious disease)." (PMID 33019519, 2020).
inflammatory myopathies (3 papers, 2013 to 2022). "Moreover, the expression of CCL4 and CCL5, along with their requisite receptors has been reported in biopsies from patients with inflammatory myopathies." (PMID 36426551, 2022).
psychiatric disorder (3 papers, 2019 to 2022). A disorder characterized by behavioral and/or psychological abnormalities, often accompanied by physical symptoms. "For mental illness diagnostics, it seems therefore justified to combine it with a complementary gene, to constitute a marker signature with high definition against those other disease conditions, as done here with CCL4." (PMID 31150013, 2019).
peripheral neuropathies (2 papers, 2013 to 2017). "The importance of CCL3 and CCL4 chemokine activity in the development and maintenance of neuropathic pain has been previously identified in several animal models of central and peripheral neuropathies." (PMID 28125674, 2017).
hematologic cancer (1 paper, 2022). "We also observed increased concentrations of CCL2, CCL3, CCL4, VEGFA and IL-1β in Severe-Death hematologic cancer patients." (PMID 36700209, 2022). "Within the hematologic cancer patient cohort there was a striking increase in the levels of the chemokines CCL2, CCL3, CCL4, CXCL8, and the cytokine IL-1β, in the Severe-Death group compared to the Mild group." (PMID 36700209, 2022).
retinopathy (1 paper, 2015). "Ccl4 also interacts with Ccr5, to promote recruitment of monocytes into the retina when subjected to oxygen induced retinopathy." (PMID 25595590, 2015).
CCL4 also shares sentences with these, for which no sentence is quoted: pneumonia (6 papers); Crohn disease (5); hepatitis (5); portal hypertension (5); post-traumatic stress disorder (4); chronic obstructive pulmonary disease (3); cognitive decline (3); dry eye (3); gestational hypertension (3); lymph node (3); metabolic disease (3); Parkinson disease (3); peritonitis (3); acute lung injury (2); alcoholic fatty liver disease (2); alcoholic liver diseases (2); autoimmune hemolytic anemia (2); brain diseases (2); brain tumor (2); celiac disease (2); cholestatic jaundice (2); chronic bronchitis (2); cystic fibrosis (2); dental caries (2); diabetic neuropathy (2); diabetic retinopathy (2); disc degeneration (2); endometrial carcinoma (2); familial hypercholesterolemia (2); frontotemporal dementia (2).
A further 142 diseases each share a sentence with CCL4 in 2 papers or fewer.